PGBD2 (piggyBac transposable element derived 2)
Tractability: PROTAC: ubiquitination databases record sites on it.
Gene: Protein-coding gene on chromosome 1 (248,906,196 to 248,919,946, forward strand). Ensembl gene ENSG00000185220.
Subcellular location (Human Protein Atlas): Vesicles
Gene Ontology:
Molecular function: sequence-specific DNA binding
Genetic constraint (gnomAD): Loss-of-function variants: 6 observed, 7.65 expected, observed/expected ratio (o/e) 0.78, 90% interval 0.43 to 1.52. That is too few expected variants to judge how well the gene tolerates losing a copy. Missense variants: 797 observed, 773.42 expected, observed/expected ratio (o/e) 1.03, 90% interval 0.97 to 1.09. Synonymous variants: 316 observed, 286.66 expected, observed/expected ratio (o/e) 1.1, 90% interval 1 to 1.21.
Homologues: Orthologues: macaque PGBD2 (99% identical), chimpanzee PGBD2 (99% identical), pig PGBD2 (90% identical), rabbit PGBD2 (89% identical), dog PGBD2 (88% identical).
Diseases named in the same sentence as PGBD2 in open-access papers:
PGBD2 is named in the same sentence as 1 disease in open-access papers, as found by Europe PMC text mining. Sharing a sentence is not in itself a finding about the gene and the disease. The quoted sentences say what the papers report.
myopia (2 papers, 2023 to 2024). "The results revealed that NR1D1, PPP1R18, PGBD2, and PPP1R3D genes were associated with myopia, and these genes were potential biomarkers for myopia." (PMID 39597899, 2024). "PGBD2 is a member of the PiggyBac family, and there are few studies on the relationship between PGBD2 and myopia." (PMID 37740201, 2023). "The biomarkers selected by both algorithms were plotted in a Venn diagram, and a total of 4 genes (NR1D1, PPP1R18, PGBD2, PPP1R3D) were identified as biomarkers of myopia in the overlapping part." (PMID 37740201, 2023). "Our study shows that NR1D1, PPP1R18, PGBD2, and PPP1R3D are effective as biomarkers in the diagnosis of myopia and that NR1D1, PPP1R18, PGBD2, and PPP1R3D may be potential therapeutic targets." (PMID 37740201, 2023).